RPS19BP1 (ribosomal protein S19 binding protein 1)
Description:
Part of the small subunit (SSU) processome, first precursor of the small eukaryotic ribosomal subunit. During the assembly of the SSU processome in the nucleolus, many ribosome biogenesis factors, an RNA chaperone and ribosomal proteins associate with the nascent pre-rRNA and work in concert to generate RNA folding, modifications, rearrangements and cleavage as well as targeted degradation of pre-ribosomal RNA by the RNA exosome. Acts as a chaperone that specifically mediates the integration of RPS19 in state post-A1. Direct regulator of SIRT1.
Synonyms: S19BP; AROS; FLJ21770; MGC52010
Tractability: Small molecule: a structure with a bound ligand is known. PROTAC: ubiquitination databases record sites on it; its protein half-life has been measured.
Gene: Protein-coding gene on chromosome 22 (39,529,088 to 39,532,767, reverse strand). Ensembl gene ENSG00000187051.
Subcellular location: Nucleus, nucleolus
Subcellular location (Human Protein Atlas): Nucleoli; Cytosol; Nucleoplasm
Pathways (Reactome):
Cellular responses to stimuli: Regulation of HSF1-mediated heat shock response
Gene Ontology:
Molecular function: enzyme binding; protein binding; RNA binding
Biological process: ribosomal small subunit biogenesis
Cellular component: nucleolus; small-subunit processome; nucleoplasm
Genetic constraint (gnomAD): Loss-of-function variants: 14 observed, 17.29 expected, observed/expected ratio (o/e) 0.81, 90% interval 0.53 to 1.27. The upper end of that interval is the gene's LOEUF score, 1.27, which puts it in group 5 of 6, group 1 being the genes least tolerant of losing a copy. Missense variants: 188 observed, 186.96 expected, observed/expected ratio (o/e) 1.01, 90% interval 0.89 to 1.13. Synonymous variants: 90 observed, 78.54 expected, observed/expected ratio (o/e) 1.15, 90% interval 0.96 to 1.37.
Homologues: Orthologues: chimpanzee RPS19BP1 (100% identical), macaque RPS19BP1 (97% identical), guinea pig RPS19BP1 (81% identical), mouse Rps19bp1 (77% identical), rat Rps19bp1 (77% identical), pig RPS19BP1 (76% identical), zebrafish rps19bp1 (36% identical), tropical clawed frog rps19bp1 (34% identical).
Diseases named in the same sentence as RPS19BP1 in open-access papers:
RPS19BP1 is named in the same sentence as 8 diseases in open-access papers, as found by Europe PMC text mining. Sharing a sentence is not in itself a finding about the gene and the disease.
prostate carcinoma (1 paper, 2023). A carcinoma that arises from epithelial cells of the prostate gland.
cancer (2 papers, 2013 to 2021). A tumor composed of atypical neoplastic, often pleomorphic cells that invade other tissues.
RPS19BP1 also shares sentences with these, for which no sentence is quoted: neuroblastoma (2 papers); type 2 diabetes (2); brain tumor (1); breast carcinoma (1); pulmonary fibrosis (1); tumor (1).